MIR4729 (microRNA 4729)
Synonyms: hsa-mir-4729
Gene: MicroRNA gene on chromosome 17 (59,366,083 to 59,366,154, forward strand). Ensembl gene ENSG00000263857.
Homologues: Orthologues: chimpanzee MIR4729 (100% identical).